ACSS1 (acyl-CoA synthetase short chain family member 1)
Description:
Catalyzes the synthesis of acetyl-CoA from short-chain fatty acids. Acetate is the preferred substrate. Can also utilize propionate with a much lower affinity (By similarity). Provides acetyl-CoA that is utilized mainly for oxidation under ketogenic conditions (By similarity). Involved in thermogenesis under ketogenic conditions, using acetate as a vital fuel when carbohydrate availability is insufficient (By similarity).
Synonyms: ACAS2L; dJ568C11.3; AceCS2L; MGC33843; ACECS1
Tractability: Small molecule: a structure with a bound ligand is known. PROTAC: ubiquitination databases record sites on it; its protein half-life has been measured.
Gene: Protein-coding gene on chromosome 20 (25,006,230 to 25,058,980, reverse strand). Ensembl gene ENSG00000154930.
Subcellular location: Mitochondrion matrix
Pathways (Reactome):
Metabolism: Ethanol oxidation
Gene Ontology:
Molecular function: acetate-CoA ligase activity; protein binding; propionate-CoA ligase activity; AMP binding; CoA-ligase activity
Biological process: acetyl-CoA biosynthetic process; ethanol catabolic process; acetate biosynthetic process; propionate biosynthetic process
Cellular component: mitochondrial matrix; mitochondrion
Genetic constraint (gnomAD): Loss-of-function variants: 42 observed, 76.25 expected, observed/expected ratio (o/e) 0.55, 90% interval 0.43 to 0.71. The upper end of that interval is the gene's LOEUF score, 0.71, which puts it in group 2 of 6, group 1 being the genes least tolerant of losing a copy. Missense variants: 782 observed, 939.63 expected, observed/expected ratio (o/e) 0.83, 90% interval 0.78 to 0.88. Synonymous variants: 380 observed, 373.76 expected, observed/expected ratio (o/e) 1.02, 90% interval 0.93 to 1.11.
Homologues: Orthologues: chimpanzee ACSS1 (99% identical), macaque ACSS1 (97% identical), mouse Acss1 (87% identical), rat Acss1 (86% identical), dog ACSS1 (85% identical), rabbit ACSS1 (81% identical), guinea pig ACSS1 (79% identical), pig ACSS1 (75% identical), tropical clawed frog acss1 (71% identical), zebrafish acss1 (68% identical). Paralogues in human: ACSS2 (45% identical), ACSS3 (32% identical), ACSM5 (23% identical), ACSM1 (23% identical), ACSM3 (23% identical), AACS (23% identical), ACSM2A (23% identical), ACSM2B (22% identical), ACSM4 (22% identical), ACSF2 (19% identical), ACSF3 (17% identical), ACSM6 (14% identical), and 1 more.
Diseases named in the same sentence as ACSS1 in open-access papers:
ACSS1 is named in the same sentence as 36 diseases in open-access papers, as found by Europe PMC text mining. Sharing a sentence is not in itself a finding about the gene and the disease. The quoted sentences say what the papers report.
breast carcinoma (5 papers, 2021 to 2025). "Through integrative analysis of TCGA and GEO datasets combined with quantitative proteomics, we identified acetyl-CoA synthetase 1 (ACSS1) as a key driver of radioresistance in breast cancer." (PMID 41413018, 2025). "Targeting ACSS1 represents a promising therapeutic strategy to sensitize tumours to radiotherapy and improve clinical outcomes in breast cancer patients." (PMID 41413018, 2025). "ACSS1 is aberrantly overexpressed in breast cancer and correlates with poor prognosis following radiotherapy." (PMID 41413018, 2025). "ACSS silencing reduces the proliferation of breast cancer, where the depletion of ACSS1/2 leads to a significant decrease in cell viability." (PMID 38610991, 2024). "Our findings reveal that ACSS1 orchestrates acetyl-CoA-driven histone acetylation to enhance DNA repair efficiency, highlighting a metabolic-epigenetic crosstalk that sustains radioresistance in breast cancer." (PMID 41413018, 2025). "The top five genes (NAT1, PPM1H, AREG, ACSS1, CXCL1) with the greatest differences in Z-scores were evaluated in the PIK3CA mutant breast cancer samples from TCGA." (PMID 38802751, 2024). "The identified ACSS1 in bladder cancer and predicted FOXM1-targets interactions in breast cancer are both validated." (PMID 33667222, 2021). "Additionally, ACSS1 and 2 are effectors for 4-hydroxytamoxifen (4-OHT), which can induce metabolic changes and promote cell survival in ER+ breast cancer." (PMID 38610991, 2024). "The identified ACSS1 is experimentally validated to promote epithelial-to-mesenchymal transition of bladder cancer cells, and the predicted FOXM1-targets interactions are verified and are predictive of relapse in breast cancer." (PMID 33667222, 2021).
glioma (3 papers, 2018 to 2025). A benign or malignant brain and spinal cord tumor that arises from glial cells (astrocytes, oligodendrocytes, ependymal cells). "For example, ACSS1 was in most pathway modules of glioma because it only occurred in highly mutated samples, which had most pathways dysregulated." (PMID 33819263, 2021).
hepatocellular carcinoma (3 papers, 2016 to 2024). A malignant tumor that arises from hepatocytes. "More importantly, human hepatocellular carcinoma with high ACSS1/2 expression exhibit increased histone H3 acetylation and FASN expression." (PMID 27357947, 2016).
bladder cancer (2 papers, 2021 to 2024). "Furthermore, our result suggests that the up-regulation of ACSS1 might play a crucial role in the bladder cancer progression by promoting EMT program." (PMID 33667222, 2021). "In the case study of bladder cancer progression, we have demonstrated that ACSS1 and PTNT12 played important roles in EMT during bladder cancer progression from UC to SARC and their expressions dynamically changed over the progression." (PMID 33667222, 2021). "We managed to validate the role of ACSS1 in EMT during bladder cancer progression, which has not been reported previously." (PMID 33667222, 2021).
gastric cancer (2 papers, 2020 to 2024). A primary or metastatic malignant neoplasm involving the stomach. "However, others had no reported cell type-specific expression or function, such as ACSS1, a mitochondrial matrix protein functioning as a catalyst of acetyl-CoA synthesis and MFSD4, a marker for hepatic metastasis in gastric cancer." (PMID 38355543, 2024).
liver cancer (2 papers, 2024). An epithelial or non-epithelial malignant neoplasm that arises from the liver. "In liver cancer cells, acetate-induced lipogenesis is regulated by ACSS2 and ACSS1 and is associated with regulation of FASN expression." (PMID 38818373, 2024).
anemia (1 paper, 2018). A reduction in the number of red blood cells, the amount of hemoglobin, and/or the volume of packed red blood cells. "As expected, anemia rats showed obvious inhibition of ACSS1 and COASY." (PMID 29551975, 2018).
cardiac hypertrophy (1 paper, 2020). "Fatty acid oxidation (Acadm, Etfdh, Acadl, Acadvl, Eci1, Hadh, Phyh, Acaa2, Hadha, Hadhb, Cd36), glucose metabolism (Dld, Pdha1, Pgam1, Pgam2, Acss1, Ldhb, Fh1, Slc2a4, Aldh6a1), TCA cycle (Aco2, Dld, Fh1, Ogdh, Sucla2, Sdha, Idh3b, Idh2) were up-regulated by hispidulin in cardiac hypertrophy." (PMID 33324687, 2020).
cervical cancer (1 paper, 2021). A primary or metastatic malignant neoplasm involving the cervix. "To confirm the importance of ACSS2 in cervical cancer, we compared the levels of ACSS1~3 in the TPM of the female genital tract and the results showed that ACSS2 was abundant in the cervix." (PMID 34206705, 2021). "We further tested the mRNA levels of ACSS1~3 in multiple cervical cancer cells and our results revealed that the expression of ACSS2 was higher than the other two genes in Hela and CaSki cells." (PMID 34206705, 2021).
colitis (1 paper, 2023). Inflammation of the colon. "We observed several upregulated genes associated with colitis and IBD development, including ABCA2, Acss1, Araf, CSAD, Ilf3, and TRAFD1, showing similar fold change patterns across treatment groups." (PMID 37909786, 2023).
tumor (22 papers, 2016 to 2025). "Second, the α2M*/CS-GRP78 axis induced ACLY and ACSS1 expression is then associated with acetyl-CoA production which activates acetylation of histone and proteins for tumor growth." (PMID 29296215, 2017). "In the differential expression analysis between high- and low-expressing ACSS1 HCC tumours, it was seen that high ACSS1 was associated with the suppression of FAO and increased PKM, a combination that has been previously linked to hypoxia and de-differentiation in HCC." (PMID 32201876, 2021). "ACSS1 and ERO1A are highly expressed in tumors and can promote tumor progression metabolic changes associated with cancer cell survival." (PMID 37101691, 2023). "To perform a statistical analysis of the association between ACSS1/2 and histone acetylation, we divided tumour samples into two groups based on ACSS1/2 signature (high versus low)." (PMID 27357947, 2016). "Third, the α2M*/CS-GRP78 mediated AKT activation regulates ACLY and ACSS1 expression which might plays a critical role in integrating cellular metabolism with signal transduction to drive tumor growth in response to environmental constraints." (PMID 29296215, 2017). "In our study, Both CS and ACSS1 gene expression were found increased in HCC tumor tissues." (PMID 27363021, 2016). "Notably, ACSS1 can catalyze the production of acetyl-CoA from acetic acid in immune cells within the tumor microenvironment, thereby promoting the proliferation of T cells and NK cells and contributing to the clearance of tumor cells." (PMID 40399304, 2025). "Furthermore, knockdown of either ACSS1 or ACSS2 significantly reduced tumor growth in mice." (PMID 35798917, 2022). "The critical enzymes for synthesizing acetyl-CoA, including adenosine triphosphate (ATP)-citrate lyase (ACLY), acetyl-CoA synthetase 1 (ACSS1), and acetyl-CoA synthetase 2 (ACSS2), are observed to have important effects in promoting tumor progression." (PMID 37122003, 2023). "In agreement with the prognostic characteristics of the ACSS1 and ACSS2 enzymes it was seen in HCC subtype-specific GEMs that iHCC1 tumours favourably expressed ACSS2, iHCC2 tumours ACSS3, whereas iHCC3 tumours ACSS1 for acetate utilisation." (PMID 32201876, 2021). "Tumor cell surface GRP78 of activated α2-macroglobulin signals regulate tumor cell proliferation by inducing and activating ACLY and ACSS1 expression to generate acetyl-CoA." (PMID 35004688, 2021). "In comparison, the fusion transcripts RP11_17A19.1-KCTD1, ZNF841-ZNF432, and ACSS1-APMAP show a common presence in normal samples as well, but they were found to be overexpressed in tumor vs. benign tissues (p < 0.05, Wilcoxon rank-test)." (PMID 28467780, 2017). "A surprising implication of this study is that acetate regulates the expression of ACLY and ACSS1 through a feed forward activation of AKT signaling to maintain acetyl-CoA production which drives histone acetylation and tumor proliferation." (PMID 29296215, 2017). "Upregulated genes such as ACSS1 (log2fc =0.50), PFKFB2 (log2fc = 0.57), GCK (log2fc =0.59), and PGAM2 (log2fc =0.59) indicate potential metabolic adaptations that may support tumour growth, though their impact is less pronounced compared to the WWOX/HIF1A ratio." (PMID 41007296, 2025). "Given that we have already highlighted similarities in the acetate utilisation of high ACSS1 tumours and iHCC3 tumours, it is not inconceivable that these three independent subsets of HCC may not be mutually exclusive." (PMID 32201876, 2021). "Further, IHC scoring showed that the expression of ACLY, ACSS2, and PDH was higher in tumor tissues than in adjacent normal tissues, and there was no linear correlation between the expression level of ACLY, ACSS1, ACSS2, and PDH." (PMID 40791180, 2025).
cancer (21 papers, 2005 to 2024). A tumor composed of atypical neoplastic, often pleomorphic cells that invade other tissues. "Endogenous acetate is vital for cancer cell proliferation as shown by reduced cell growth in cells where ACSS1/2 is silenced, whereas exogenous acetate reduces cell proliferation." (PMID 33937302, 2021). "ACSS1 was associated with iHCC3, which had the lowest survival rate, whereas ACSS2 was associated with the moderate survival rate cancers (iHCC2) and ACSS3 was associated with the subtype having the longest patient survival rate (iHCC1)." (PMID 33304273, 2020). "In cancer cells ACLYi alone suppressed α2M*-induced acetyl-CoA production whereas acetate restored this event which indicates that ACSS1 can compensate depending on acetate availability." (PMID 29296215, 2017). "The higher percentage of ACSS1 high-expression cases than that of ACSS2 fully proves the importance of ACSS1 in acetate utilization by cancer." (PMID 27357947, 2016). "ACSS1/2 upregulation suggests that these cancer cells utilize acetate as both epigenetic metabolite and carbon source to meet their growth needs." (PMID 27357947, 2016). "Both ACSS1 and ACSS2 have been implicated in acetate utilization by cancer cells." (PMID 33304273, 2020). "Therefore, we hypothesized that the temporal dynamics of EMT regulatory genes (e.g., ACSS1 or PTPN12) could be exploited to predict cancer progression." (PMID 33667222, 2021). "Moreover, it has also been reported that increased ACSS1/2 expression could lead to the import of short‐chain fatty acid (C11), which switches cancer cells from glucose to fatty‐acid utilization." (PMID 29493120, 2018). "For example, acetyl coenzyme A (CoA) synthetase 1 (ACSS1) and acetyl CoA synthetase 2 (ACSS2) have been shown to play a role in regulating how cancer cells utilize acetate, enhancing their ability to use acetate as an additional nutrition source." (PMID 39519507, 2024). "EPHX2, ACSF2, CYP27A1, ACSS1, and ALDH1L1 showed hypermethylation in several types of human cancer; on the contrary, AKR1B10, POLG2, NDUFB8, ACACB, and MRPS22 consistently showed hypomethylation in several types of human cancer." (PMID 37223030, 2023). "Also, ACSS1 and ACSS2 expression levels can affect the net acetate uptake rates in several cancer types." (PMID 38851813, 2024). "The rescue of hypoxia-reduced ACSS1 and ACSS2 expression by acetate may indicate that ACSS1 and ACSS2 play an important role in cancer cells adapting to hypoxia." (PMID 27357947, 2016). "As the major enzymes in acetate metabolism, ACSS1 and ACSS2 may merit further explorations as a therapeutic target for cancer." (PMID 27357947, 2016). "These discrepancies will have to be reconciled by future studies that demonstrate whether ACSS3 can indeed utilize acetate at concentrations and conditions found in the mitochondrial matrix, and that ACSS1 is not the preferred route in some cancers." (PMID 33304273, 2020). "The mitochondrial forms, ACSS1 and ACSS3, most likely play a significant role in energy derivation via oxidation of acetate and propionate, respectively, but may be less involved in regulatory functions in cancer cells than ACSS2." (PMID 33304273, 2020). "Importantly, the enzyme activity of both CS and ACSS1 have been reported to be increased in HCC and these two enzymes catalyze the reactions that provide alternative sources of energy and substrates for multiple rapid proliferating cancer cells including HCC cells." (PMID 27363021, 2016).
ACSS1 also shares sentences with these, for which no sentence is quoted: colon cancer (3 papers); Obesity (3); myeloma (2); non-small cell lung carcinoma (2); renal cell carcinoma (2); acute kidney injury (1); Alzheimer disease (1); Atrophy (1); brain tumor (1); cannabis dependence (1); cardiomyopathies (1); cervical squamous cell carcinoma (1); Crohn disease (1); diabetic nephropathy (1); glioblastoma (1); Hypoglycemia (1); intestinal cancer (1); nicotine dependence (1); osteosarcoma (1); ovarian carcinoma (1); sarcopenia (1); Sepsis (1); tauopathies (1); triple-negative breast carcinoma (1).